ALB (albumin)
Diseases named in the same sentence as ALB in open-access papers (continued):
Sharing a sentence is not in itself a finding about the gene and the disease.
diabetes (continued). "The risk factors for stroke for all dialysis patients were older age, diabetes, and CVD, whereas lower albumin-corrected calcium was a predictor in HD patients and higher triglyceride levels were associated with an increased risk of stroke in PD patients." (PMID 26485155, 2015). "The TG/HDL-C ratio was an independent determinant of FMD (β = 0.25 p = 0.02) together with the TG, HDL-C, hsCRP, serum albumin, phosphate levels, SBP, PTH, eGFR and the presence of diabetes mellitus." (PMID 25885289, 2015). "Age, hemoglobin, phosphorus, albumin, potassium, 24-h urine volume, SGA, and diabetes were variables with P<0.2 in the univariate analysis of patient survival among PD patients." (PMID 26121574, 2015). "FPG, HOMA-IR, albumin, Alb/Cr, TC, LDL-C, phosphate, percentage of the subjects with LVH and micro-albuminuria, and duration of diabetes differed across albumin-adjusted serum calcium quartiles." (PMID 25924883, 2015). "Compared with those with a lower BMI, male patients with a higher BMI were more likely to have a younger age, a higher prevalence of diabetes and hypertension, as well as higher levels of MAP, eGFR, albumin, hemoglobin, and HbA1C." (PMID 25942584, 2015). "Albumin excretion rate (AER) rose with increasing age (p = 0.008, r = 0.31) and diabetes duration (p = 0.017, r = 0.29), but remained within normal range in all patients." (PMID 24667016, 2014). "On multivariate Cox regression analysis, only higher HS-CRP level, older age, the presence of diabetes mellitus (DM), lower serum albumin level, and the occurrence of cardiovascular events during follow-up were identified as independent predictors of mortality." (PMID 24667814, 2014). "The Diabetes Control and Complications Trial (DCCT) demonstrated that there was a strong relationship between diabetic retinopathy and elevated albumin excretion." (PMID 23618325, 2013). "BMI, SBP, cholesterol, triglycerides, CRP, cystatin c, serum GGT and diabetes prevalence increased with the age while HDL and serum albumin were opposite." (PMID 23947772, 2013). "The results of univariate Cox regression analysis indicated that skin autofluorescence was a predictor of development of the primary kidney end point, together with diabetes, dyslipidemia, estimated GFR, amount of proteinuria and serum albumin." (PMID 24349550, 2013). "In the present study, 21 weeks diabetes by STZ produced a diabetic nephropathy which was manifested by increased creatinine, creatinine clearance, serum BUN, and 24 h urinary albumin." (PMID 24223616, 2013). "The patients with T1DM and confirmed NPDR had a longer duration of diabetes, higher serum HbA1c levels, higher CRP, higher urinary albumin excretion, and systolic blood pressure values compared to the T1DM patients without retinopathy (P < 0.05)." (PMID 23671881, 2013). "The independent determinants of skin autofluorescence in this study were age, diabetes, estimated GFR, proteinuria, serum albumin and hemoglobin." (PMID 24349550, 2013). "Age, serum albumin, hemoglobin, UF volume, and SBP were also significant prognostic factors of death in both tKt/V and rKt/V models, but BMI and diabetes were significant only in the tKt/V model." (PMID 23369065, 2013). "Other covariables with p-value < 0.25 in the univariate analysis were age, BMI, serum albumin, hemoglobin, UF volume, SBP, and diabetes." (PMID 23369065, 2013). "In the univariate Cox proportional hazards model, age, presence of diabetes or CVD, serum albumin concentration, Log10CRP level, peritoneal Kt/V urea, nPCR, %LBM, RRF, and PrCl were significantly associated with mortality." (PMID 23418538, 2013). "Contrary to Group 1, Group 4 had the lower prevalence of diabetes and level of hs-CRP, as well as higher levels of serum pre-albumin, albumin, creatinine, and nPCR." (PMID 24305468, 2013).
diabetes (continued). "As the concentration of cystatin C rose, the levels of age, diabetes duration, carotid and femoral IMT, systolic blood pressure, neutrophils, BUN, Cr, UA and CRP increased, but RBC, Hb, PLT, albumin, FPG, PPG and GFR decreased." (PMID 23843968, 2013). "Ten explanatory variables were included: GFR, age, gender, CVD, diabetes, Hb, log CRP, p-albumin, MAP and BMI." (PMID 22710013, 2012). "In the current study, significant decline in serum albumin level and elevations in markers of liver injury (ALT, AST, ALP, and bilirubin) reflects the hepatocytes injury in experimental diabetes." (PMID 22956978, 2012). "Participants of the EPIC-NL study were more likely to be women, and to have hypertension and parental history of diabetes, whereas participants of the PREVEND study were more likely to be smoker and had slightly higher uric acid and albumin on average." (PMID 23284703, 2012). "In multivariate analysis, after adjusting for diabetes status, age, gender, HD vintage, Kt/Vurea, WC, fetuin A, chemerin, hs-CRP, albumin and CaXP levels, higher fetuin A levels significantly predicted the diagnosis of hepatic steatosis by HRIs (P<0.001)." (PMID 22815691, 2012). "The relationship between glycemic control and lipid abnormalities with urinary albumin-creatinine ratio (ACR) in chronic kidney disease (CKD) patients with diabetes mellitus (DM) is unknown." (PMID 22958709, 2012). "We postulate that this may reflect the risk of MRSA sequelae not only among tertiary care patient populations, but also among MRSA-positive inpatients with the identified risk factors of advanced age, diabetes, renal insufficiency, or decreased albumin, regardless of hospital type or location." (PMID 21949707, 2011). "The cause of albumin alteration is not clear, we hypothesize an influence of several factors, which in this specific situation are the generation of free radicals by cobalt, a genetic predisposition or a possible influence of diabetes." (PMID 22084701, 2011). "In Type 2 diabetic patients the duration of diabetes was the strongest predictor; SBP and serum creatinine as well predicted increased albumin excretion rate." (PMID 17224056, 2007). "Regardless of age, diabetes status, and physical activity and serum albumin levels, women showed higher odds of ASB than did men." (PMID 41843590, 2026). "A study involving 423 participants analyzed AFB1-albumin adduct levels concerning various metabolic conditions, including diabetes, obesity, central obesity, metabolic syndrome, and non-alcoholic fatty liver disease (NAFLD)." (PMID 39891869, 2025). "Other covariates (CRP, albumin, diabetes, hypertension, CKD, ischemic heart disease): not statistically significant after adjustment." (PMID 41195122, 2025). "Among laboratory tests, patients with diabetes showed significantly higher ALT activity, bilirubin, creatinine, and baseline HCV RNA levels, while albumin, haemoglobin, and platelet counts were significantly lower in them compared to the group without DM (p < 0.001)." (PMID 40593165, 2025). "We checked diabetes-related macro- and microvascular complications, which were negative, except in one episode, trace albumin was present in urine, which was negative on subsequent investigations." (PMID 40585621, 2025). "The relationship between the Blood Urea Nitrogen to Albumin Ratio (BAR) and cardiovascular diseases in diabetes, as well as cardiovascular and all-cause mortality, is not yet entirely understood." (PMID 40290308, 2025). "To further refine our model, we employed LASSO regression analysis, which selected the following variables: CD4 count, Hb, platelet count (PLT), ALB, VD, lumber spine BMD, current smoking status, diabetes, history of falls, TDF usage, and HIV RNA load (1000-100000 copies/mL)." (PMID 40160472, 2025).
diabetes (continued). "Participants in the SUA (T3) group exhibited higher levels of age, BMI, WBC, HGB, HCT, GGT, ALB, P, Ca, sCr, BUN, TG, Hcy, BMD, as well as a greater prevalence of cardiovascular events, hypertension, diabetes, current smokers, and current drinkers compared to the other groups." (PMID 40978736, 2025). "Among these patients, those with high levels of log2(EASIX) exhibited increased levels of RDW, liver damage and kidney damage, SOFA and APS III, higher proportion of hypertension, diabetes, AKI, CKD and CRRT, decreased levels of blood pressure, hemoglobin, platelets, albumin." (PMID 40375932, 2025). "In patients with EPN without diabetes, urinary albumin is believed to be acting as a substrate for the organism." (PMID 40255825, 2025). "Of particular interest, subgroup analyses of all patients revealed that dotinurad had an albumin-lowering effect regardless of the presence of diabetes." (PMID 40839334, 2025). "The results of the univariate analysis revealed significant associations between TISVAP-related infections and several factors, including gender, BMI, ECOG performance status (ECOG_score), history of diabetes, TNM staging, metastasis, type of chemotherapy, WBC count, and serum albumin levels." (PMID 39773012, 2025). "When compared to the EH group, the PA group had lower serum potassium and heart rate (P < 0.05), but higher diabetes prevalence, standing plasma aldosterone concentration (PAC), serum sodium, albumin-to-creatinine ratio (ACR), and 24-hour urinary potassium excretion (P < 0.05)." (PMID 40862117, 2025). "Finally, our dataset may include patients with comorbidities such as renal disease and diabetes, the medication regimen before blood samples were collected for lactate and albumin determination was unclear, which could potentially affect lactate and albumin levels." (PMID 40155840, 2025). "Albumin from healthy persons, both alone or in complexes with either resveratrol or DHLA, was more resistant to structural change in the presence of AAPH (smaller ΔF min-1) than albumin from persons with diabetes." (PMID 41321387, 2025). "In addition, hemoglobin (p < 0.001), albumin (p = 0.010), and PNI scores (p = 0.014) were lower in patients with diabetes." (PMID 40283031, 2025). "Model 3 was a comprehensively adjusted model that accounted for variables such as sex, age, ECOG performance status, smoking, alcohol, cardiovascular disease, diabetes, hypertriglyceridemia, chemotherapy regimen, immunotherapy, targeted therapy, LDH, ALB, LDL, EBV_DNA, T_stage, and N_stage." (PMID 41019567, 2025). "Heat-related illness.Occupational heat stress.Construction workers.Measured kidney injury using the urinary albumin–creatinine ratio (ACR) from urine samples, hydration status, sleep duration, body mass index (BMI), obesity, diabetes, hypertension, and shift length." (PMID 41302597, 2025). "Patients in the intermediate and high NFS groups were found to be older, had a higher prevalence of hypertension, longer duration of diabetes, and had higher DBP, HR, HbA1c, TC, LDL-C, ALT, ALB, and platelet numbers when compared with those in the low NFS group (all P < 0.001)." (PMID 40751154, 2025). "Albumin values also differed significantly with weak effect sizes between GIH patients with or without diabetes mellitus." (PMID 40863037, 2025). "Background/Objectives: The current standard of care for assessing chronic kidney disease complicating diabetes (DKD) includes measurement of estimated glomerular filtration rate (eGFR) and urinary albumin:creatinine ratio (uACR) but both tests have limitations." (PMID 40150005, 2025). "The base value of the ET model is E f(x) = −0.25, and the patient did not transfusion albumin, corresponding to f(x) = −0.04; patient had no diabetes, corresponding to f(x) = −0.03." (PMID 40454154, 2025). "We quantified miR-200a-3p urinary EV levels in hypertensive patients with and without diabetes (n = 69), 42 of which were with increased urinary albumin excretion (UAE)." (PMID 40723868, 2025).
diabetes (continued). "We evaluated the patient for diabetes-related macrovascular and microvascular complications, all of which were negative, except for one episode in which trace albumin was detected in the urine; however, this finding was not confirmed on subsequent testing." (PMID 40585621, 2025). "In these countries, predictive indicators such as HbA1c, duration of diabetes, and the urinary albumin-to-creatinine ratio (UACR) are not only easily accessible but also relatively low in cost, making them an ideal choice in resource-limited settings." (PMID 40717809, 2025). "As a novel comprehensive inflammatory biomarker, the red cell distribution width-to-albumin ratio (RAR) has been proven to be involved in the occurrence and development of various inflammatory diseases, such as diabetes mellitus, stroke, and chronic kidney disease." (PMID 40783688, 2025). "Regular blood pressure measurements should be conducted at every clinical visit, and a spot urine albumin–creatinine ratio (UACR) should be measured at baseline and at least annually or more frequently in people with comorbidities such as diabetes mellitus or pre-existing renal dysfunction." (PMID 41302171, 2025). "None received neoadjuvant therapy, and no patients had diabetes; preoperative albumin was 38.77 ± 3.58 g/L." (PMID 41404061, 2025). "In the fully adjusted model, which included age, gender, smoking, hypertension, diabetes, CKD, ApoA1, ApoB, albumin, uric acid, eGFR, fibrinogen, LVEF, and Gensini score, Lp(a) remained linearly and positively associated with all-cause and cardiovascular mortality (P-nonlinear = 0.528 and 0.859)." (PMID 40496568, 2025). "The baseline conditions associated with higher uACR levels included younger age, male sex, diabetes comorbidity, higher systolic blood pressure, lower eGFR and serum albumin, and absence of RASi use." (PMID 38688876, 2025). "For instance, one study demonstrated that higher fructosamine and glycated albumin demonstrated increased HR for PAD and CLI, particularly with patients diagnosed with diabetes and those with a higher glycemic index, and remained significant, even after adjusting for cardiovascular risk factors." (PMID 40278353, 2025). "Six independent predictors—age, duration of type 2 diabetes mellitus (T2DM Duration), systolic blood pressure (SBP), urinary albumin-to-creatinine ratio (UACR), left atrial diameter (LAD), and left ventricular posterior wall thickness at end-diastole (LVPWd)—were incorporated." (PMID 40862125, 2025). "However, significant differences were observed in terms of diabetes, heart rate, LVEF, and serum levels of ALT, AST, and albumin." (PMID 40069854, 2025). "The best predictors of 1-, 3-, and 5-year all-cause mortality contained nine independent factors, including age, body mass index (BMI), diabetes mellitus (DM), cardiovascular disease (CVD), cancer, urine volume, hemoglobin (HGB), albumin (ALB), and pleural effusion (PE)." (PMID 38415296, 2024). "The univariable analysis showed that age, sex, race/ethnicity, education level, PIR, smoking status, alcohol consumption, hypertension, diabetes, CVD, cancer, physical activity, albumin, uric acid, total cholesterol, eGFR, and dietary selenium intake were linked to sarcopenia." (PMID 39328467, 2024). "In terms of clinical manifestations, DN patients have lower renal function such as elevated serum creatinine, urea, urinary albumin, and UACR, in addition to the main manifestations of diabetes mellitus such as hyperglycemia, polyphagia, polydipsia, polyuria, and wasting." (PMID 37991543, 2024). "This association holds regardless of the presence of comorbid hypertension and diabetes or the severity of urinary albumin levels." (PMID 38558798, 2024).
diabetes (continued). "Furthermore, based on our study, decreased Na and/or decreased ALB, and/or increased urea and/or increased RDW-SD in routinely tested patients should alert the clinician to request the measurement of HbA1c, as these findings may be associated with prediabetes or diabetes." (PMID 39125606, 2024). "Age, sex, weight and BMI, preoperative albumin and malnutrition (albumin < 3.5 g/dL), ASA class, functional status, diabetes status, smoking status, history of CHF, and hypertensive medication usage all varied significantly by preoperative weight loss (P < 0.05 all)." (PMID 38561849, 2024). "In this study, ESRD patients in the early stages of HD with diabetes had lower blood phosphorus levels, calcium-phosphorus product levels, and serum ALB and iPTH levels than nondiabetic patients." (PMID 39026232, 2024). "Non-survivors were older, had a higher frequency of diabetes, a shorter dialysis history, lower albumin, and also had increased hs-CRP and OPG levels." (PMID 39335504, 2024). "There were some differences between the BAR groups with respect to various covariates (i.e., sex, age, alcohol abuse, CKD, diabetes, hypertension, fever, asthenia, AST, BUN, ALB, creatinine, procalcitonin, APACHE II score, SOFA score, and renal replacement therapy) (P < 0.05)." (PMID 39013924, 2024). "This study did not evaluate primary diseases, such as diabetes mellitus and low serum albumin levels, as a factor predicting survival or complications." (PMID 39135880, 2024). "Stratified analyses showed such positive associations between dietary Mg and ASMI were consistent across different strata of gender, age, PIR, BMI, physical activity, diabetes, heart disease, chronic kidney disease, energy intake, CRP, serum albumin, and the use of muscle-related medications." (PMID 38509619, 2024). "Age, diabetes history, blood pressure, BUN, Scr, eGFR, SUA, Ca, P, ALB, TC, TG, LDL-C, HDL-C, iPTH, and HGB were the factors that significantly differed between the non-calcification group and the calcification group and were therefore set as independent variables." (PMID 38200088, 2024). "Groups were comparable in terms of age, preoperative BMI, ASA score, previous abdominal surgery, smoke and alcohol use, comorbidities (hypertension, cardiac, diabetes, respiratory), CCI, preoperative hemoglobin and albumin, cTNM staging, surgical technique, and operative time (p-value = ns)." (PMID 38970713, 2024). "Significant variations were observed among the DII groups concerning gender, race, education level, PIR, smoking habits, BMI, waist circumstance, WHtR, SBP, TC, HDL, ALB, ALT, GGT, PLT, hypertension, diabetes, NAFLD as well as advanced liver fibrosis (P < 0.05)." (PMID 38685122, 2024). "After adjusting for age, sex, BMI, smoking status, alcohol consumption, hypertension, diabetes, tumor size, histological type, T stage, lymph node status, cancer stage, WBC, hemoglobin, platelet count, and albumin, the partial correlation coefficient between RDW and SMI was − 0.149 (p = 0.005)." (PMID 38233827, 2024). "Statistically significant indicators in the comparison between the two groups (dialysis age, albumin, total cholesterol, low-density lipoprotein cholesterol, NLR) and clinically significant indicators (diabetes) were included in the logistic regression analysis." (PMID 39685563, 2024). "In our data, WMH volume was related to age, hypertension, diabetes, current smoking, systolic and diastolic BP, fasting glucose, low-density lipoprotein (LDL) cholesterol, white blood cell (WBC) counts, BUN, creatinine, GFR, albumin, and BAR." (PMID 38396162, 2024). "After adjusting for covariates such as gender, age, ethnicity, diabetes, mechanical ventilation use, CHF, COPD, MAP, AMI, pneumonia, rhythm, β-blocker use, SOFA score, BUN, albumin, Hct, and ALT, a trend of increasing 28-day ICU mortality with rising HR/T ratios was observed." (PMID 39735700, 2024).